IGF2BP1 (insulin like growth factor 2 mRNA binding protein 1)
Diseases named in the same sentence as IGF2BP1 in open-access papers (continued):
Sharing a sentence is not in itself a finding about the gene and the disease.
Type 2 Diabetes (3 papers, 2020 to 2025). "Using the Type 2 Diabetes Knowledge Portal, we identified strong associations between IGF2BP1 variants and body weight, as well as moderate associations with height, glycated hemoglobin, and type 2 diabetes." (PMID 40632859, 2025). "TMEM9B-AS1, down-regulated in type 2 diabetes, regulates ribosomal biogenesis in muscle by promoting IGF2BP1-MYC mRNA interaction." (PMID 40632859, 2025). "Genome-wide association studies (GWASs) have not identified any potential IGF2BP1 single-nucleotide polymorphisms (SNPs) linked to human disease whereas SNPs in the second intron of IGF2BP2 are associated with type 2 diabetes." (PMID 32154328, 2020). "Compared with IGF2BP1 and IGF2BP3, IGF2BP2 has been considered as a candidate gene for type 2 diabetes mellitus (T2D)." (PMID 36237306, 2022).
ulcerative colitis (3 papers, 2021 to 2024). An inflammatory bowel disease involving the mucosal surface of the large intestine and rectum. "We found that IGF2BP1 and IGF2BP2 expression was decreased in Crohn’s disease (CD) tissues and that IGF2BP2 was decreased in ulcerative colitis (UC) tissues compared with normal tissues (P < 0.05)." (PMID 34422815, 2021).
viral infection (3 papers, 2022 to 2023). "Despite only few studies dedicated to IGF2BP1–virus cross-talk, the broad range of virus families covered by these reports suggests a widespread role of IGF2BP1 in viral infection and the impact of viruses on IGF2BPs, especially in cancer." (PMID 37515119, 2023).
breast tumor (2 papers, 2018 to 2022). "IGF2BP1 was found to ubiquitously express in normal adult breast epithelial cells, and mouse and human breast tumor cell." (PMID 29954406, 2018). "Furthermore, IGF2BP1 can depress metastatic breast tumor cell proliferation and invasion by targeting and regulating localized expression of multiple adhesion- and motility-related mRNAs." (PMID 29954406, 2018).
cervical squamous cell carcinoma (2 papers, 2023). A squamous cell carcinoma arising from the cervical epithelium. "In cervical squamous cell carcinoma (CESC), ALKBH5 and IGF2BP1 target silent mating type information regulation 2 homolog 3 (SIRT3), reducing its stability, subsequently inhibiting ACC1 deacetylation and lipid metabolism and ultimately repressing CESC." (PMID 37055798, 2023).
cholangiocarcinoma (2 papers, 2024 to 2026). A carcinoma that arises from the intrahepatic biliary tree (intrahepatic cholangiocarcinoma) or from the junction, or adjacent to the junction, of the right and left hepatic ducts (hilar cholangiocarcinoma). "Meanwhile, we found that IGF2BP1/2/3 had higher expression levels than YTHDF1/2/3 in cholangiocarcinoma." (PMID 41513610, 2026).
colitis (2 papers, 2022 to 2024). Inflammation of the colon. "The circRNA/miRNA/mRNA competitive endogenous RNA (ceRNA) network analysis showed that the candidate miRNAs were connected to well-known colitis-associated CRC ACVR2A, SOCS1, IGF2BP1, FAM126A, and CCDC85C mRNAs, and circ-SHPRH circRNA." (PMID 38891888, 2024). "The deletion of IGF2BP1 in intestinal epithelial cells was shown to compromise barrier function and ameliorate experimental colitis in mice, thus suggesting a role for IGF2BP1 in maintaining intestinal homeostasis." (PMID 35014869, 2022).
colon adenocarcinoma (2 papers, 2021 to 2024). "A recent study reported higher expression of IGF2BP1 in colonic adenocarcinoma relative to normal colonic mucosa in a set of 13 paired samples." (PMID 38604503, 2024).
colorectal tumor (2 papers, 2017 to 2019). "IGF2BP1 is an mRNA binding oncofetal protein, not normally expressed in adult tissues, that we previously demonstrated to have a role in modulating colorectal tumor growth in vitro and in vivo, and may also play a role in early metastasis." (PMID 28787442, 2017).
depression (2 papers, 2023 to 2024). "Similarly, UBE2Z, GIP and IGF2BP1 have been linked to CAD, T2D, and depression-related traits such as insomnia, BMI, educational attainment, CRP levels, platelet count and smoking." (PMID 37390107, 2023). "Furthermore, we observed a significant positive correlation between IGF2BP1 and immune cells, specifically natural killer T cells, central memory CD4 T cells, and activated CD8 T cells, which has implications for depression immunotherapy." (PMID 38453794, 2024).
diabetic nephropathy (2 papers, 2005 to 2025). "Therefore, exploring the molecular mechanisms of IGF2BP1 is crucial for enhancing and advancing our understanding of RNA modification in diabetic nephropathy." (PMID 39945887, 2025). "IGF2BP1 expression has been reported to be elevated in the mouse model of diabetic nephropathy." (PMID 39945887, 2025).
endometriosis (2 papers, 2023 to 2025). The growth of functional endometrial tissue in anatomic sites outside the uterine body. "In endometriosis models, IGF2BP1 knockdown decreased the expression of key glycolytic enzymes, including PKM2 and HK2, and reduced glucose uptake, highlighting IGF2BP1's role in supporting metabolic reprogramming through PKM2 regulation." (PMID 41210679, 2025).
insomnia (2 papers, 2023 to 2025). A sleep disorder characterized by difficulty in falling asleep and/or remaining asleep. "Genome-wide association studies identified a genetic locus (near ATP5G1, UBE2Z, SNF8, IGF2BP1 and GIP) linked to insomnia and CVD." (PMID 40176577, 2025). "This study is the first to identify four genes at a single locus that link CVD and insomnia: ATPsynC, Bruce, lsn and Imp (ATP5G1, UBE2Z, SNF8 and IGF2BP1 in humans)." (PMID 40176577, 2025).
medulloblastoma (2 papers, 2021 to 2023). A malignant, invasive embryonal neoplasm arising from the cerebellum. "Whilst previous analysis of genetic/epigenetic changes would not have readily identified the genes identified here, some could have been identified solely through subtype-specific overexpression (as was the case for IGF2BP1 and WNT16 in ALL and ATOH1 in medulloblastoma)." (PMID 34230614, 2021).
neuroendocrine neoplasm (2 papers, 2022 to 2025). Endocrine tumors, also referred to as neuroendocrine tumors (NETs), are defined by a common phenotype which is characterized by the expression of general markers (neuron specific enolase, chromogranin, synaptophysin) and hormone secretion products. "To further investigate IGF2BP1 in human neuroendocrine tumors, we examined IGF2BP1 mRNA and protein expression in human NEN cell lines derived from pancreatic (BON1, QGP1), colon (Colo320) and lung (NCIH727) primary tumors." (PMID 35565249, 2022). "In this report, we identified the mRNA-binding protein IGF2BP1 as an important post-transcriptional regulator of EZH2-driven cell proliferation in neuroendocrine tumors." (PMID 35565249, 2022). "Our data identify IGF2BP1 as an important driver of tumor progression in NEN, and indicate that disruption of the IGF2BP1-Myc-EZH2 axis represents a promising approach for targeted therapy of neuroendocrine neoplasms." (PMID 35565249, 2022). "Taken together, our results suggest that targeting the IGF2BP1-c-Myc-EZH2 network at various levels might be a promising therapeutic approach in neuroendocrine tumors, potentially also by using combinatorial approaches, warranting further in vivo validation." (PMID 35565249, 2022). "Consistently with these literature reports, we found that IGF2BP1 affects expression of EZH2 and its downstream effectors regulating cell proliferation, such as CDK2 and CCNE1 in neuroendocrine tumor cells, thereby driving G1/S transition." (PMID 35565249, 2022).
oral squamous cell carcinoma (2 papers, 2022 to 2025). "In oral squamous cell carcinoma, METTL3 increases IGF2BP1-dependent mRNA m6A methylation of B cell-specific Moloney murine leukemia virus integration site 1 (BMI1), a polycomb complex protein, thus promoting its mRNA translation by recruiting polysomes to BMI1 mRNA." (PMID 40584294, 2025).
ovarian serous adenocarcinoma (2 papers, 2019 to 2020). An adenocarcinoma that arises from the ovary and is characterized by the presence of malignant epithelial cells that, in well differentiated tumors, resemble the epithelium of the fallopian tube or, in poorly differentiated tumors, show anaplastic features and marked nuclear atypia. "In contrast to the small gene set (IGF2BP1, SRF, FOXK1 and PDLIM7), the enlarged gene set (35 genes plus IGF2BP1 and SRF) was significantly associated with poor OS probability in serous ovarian cancer, HCC as well as LUAD, as supported by HR values ranging from 1.52 to 2.15." (PMID 30371874, 2019).
ovarian serous cystadenocarcinoma (2 papers, 2020 to 2021). A malignant serous cystic epithelial neoplasm arising from the ovary. "The expression of YTHDF1, HNRNPC, IGF2BP1, VIRMA, and HNRNPA2B1 was significantly positively correlated with the ovarian serous cystadenocarcinoma (OV) tumor stem cell score (based on DNA methylation) (DNAss)." (PMID 34150845, 2021).
retinoblastoma (2 papers, 2016 to 2021). A malignant tumor that originates in the nuclear layer of the retina. "We further verified the effect of IGF2BP1 on cell proliferation and migration capability of a retinoblastoma cell line using knockdown studies." (PMID 27799869, 2016). "Further knockdown studies of IGF2BP1 in retinoblastoma cell lines revealed it as a prospective therapeutic target for retinoblastoma." (PMID 27799869, 2016). "Insulin growth factor 2 mRNA binding protein 1 (IGF2BP1), chromogranin A, fetuin A (ASHG), Rac GTPase-activating protein 1 and midkine that were found to be overexpressed in retinoblastoma were further confirmed by immunohistochemistry by staining 15 independent retinoblastoma tissue sections." (PMID 27799869, 2016).
skin squamous cell carcinoma (2 papers, 2022 to 2025). A carcinoma arising from the squamous cells of the epidermis. "In skin squamous cell carcinoma (SCC), CRISPR/Cas9-mediated IGF2BP1 knockout reduces the levels of IGF2BP1-stabilized mRNAs, including IGF2, CD44, Gli1, and Myc, subsequently leading to the inhibition of skin SCC cell survival and proliferation." (PMID 40958857, 2025).
acute kidney injury (1 paper, 2023). Sudden and sustained deterioration of the kidney function characterized by decreased glomerular filtration rate, increased serum creatinine or oliguria. "IGF2BP1 is mainly localized in renal TECs; thus, the IGF2BP1-mediated E2F1/MIF pathway in renal TECs may be a valuable target to mitigate septic acute kidney injury." (PMID 37865763, 2023).
astrocytoma (1 paper, 2022). "In a single-cell RNA-seq analysis of astrocytoma dataset, 23 out of 28 m6A-RMRs (82%) (except ALKBH5, IGF2BP1, IGF2BP2, IGF2BP3, and G3BP2) were in the medium to high expression levels in malignant cells of astrocytoma." (PMID 35211628, 2022).
Azoospermia (1 paper, 2025). Absence of any measurable level of sperm,whereby spermatozoa cannot be observed even after centrifugation of the semen pellet. "To clarify the expression of IGF2BP1 in human testicular tissues, we performed immunostaining on human SSCs and obstructive azoospermia (OA) patient testicular tissues with normal spermatogenesis." (PMID 41280724, 2025). "Furthermore, IGF2BP1 gene variants were positively correlated with the occurrence of non-obstructive azoospermia (NOA)." (PMID 41280724, 2025).
B-cell precursor acute lymphoblastic leukemia (1 paper, 2024). "Autophagy inhibition, spleen tyrosine kinase (SYK), and IGF2BP1 are potential future therapeutic targets for ETV6::RUNX1-driven B-cell precursor acute lymphoblastic leukemia due to their roles in ETV6::RUNX1 cell survival and prognosis." (PMID 38811988, 2024).
basal cell carcinoma (1 paper, 2023). A carcinoma involving the basal cells. "Through OCLR algorithm, it can be seen that mRNAsi, EREG-MRNASI value has significant difference between the two clusters (p < 0.05), suggesting that FMR1, LRPPRC, RBMX, YTHDC2 and IGF2BP1 may affect CRC by regulating the pathway of basal cell carcinoma." (PMID 37194014, 2023).
cardiac hypertrophy (1 paper, 2021). "It has been reported that terminal differentiation-induced non-coding RNA (lncRNA TINCR) could attenuate cardiac hypertrophy by epigenetically silencing CaMKII and insulin like growth factor 2 mRNA binding protein 1 (IGF2BP1) could participate in the modification of mRNA stability." (PMID 33912556, 2021).
choriocarcinoma (1 paper, 2018). An aggressive malignant tumor arising from trophoblastic cells. "IGF2BP1 was showed to be overexpressed in both retinoblastoma and choriocarcinoma." (PMID 29954406, 2018).
endometrial adenocarcinoma (1 paper, 2021). "The expression of YTHDF1, YTHDF2, and IGF2BP1/2 was increased in women with endometrial adenocarcinoma, whereas a reduction in YTHDC1 was detected." (PMID 34149936, 2021).
endometrial tumor (1 paper, 2025). "Alternatively, the observed downregulation of pSTAT3 in high-IGF2BP1 tumors may reflect compensatory mechanisms or shifts in immune signaling dynamics unique to the endometrial tumor microenvironment." (PMID 41210679, 2025).
eosinophilia (1 paper, 2023). "IGF2BP1 high level was positively associated with the infiltration of macrophages, Th1 cells, and Th2 cells, and negatively to NK CD56 bright cells, eosinophilia, and mast cells." (PMID 36966311, 2023).
familial renal glucosuria (1 paper, 2020). Familial Renal Glucosuria (FRG) is characterized by the presence of persistent isolated glucosuria in the absence of both generalized proximal tubular dysfunction and hyperglycemia. "In conclusion, WES identified DNA variants in four different genes as potential novel causes of IKH, suggesting that IKH is a heterogeneous disorder that can be split into several novel diseases: NCOR1-KH, IGF2BP1-KH, SGLT2-KH or familial renal glucosuria KH, and NEK11-KH." (PMID 32034166, 2020).
fibrolamellar hepatocellular carcinoma (1 paper, 2022). A distinctive type of liver cell carcinoma that arises in non-cirrhotic livers and is seen predominantly in young patients.
follicular thyroid carcinoma (1 paper, 2021). "IGF2BP1 furthermore identified ATC foci within low-grade follicular thyroid carcinoma." (PMID 32719445, 2021).
hemoglobin disorders (1 paper, 2020). "Having established function of the newly constructed 2A vectors in healthy erythroblasts, we wanted to determine whether IGF2BP1 could induce HbF levels in cultured cells from patients with hemoglobin disorders." (PMID 32154328, 2020).
hepatitis B (1 paper, 2024). "Strikingly, Glaß and Hüttelmaier showed that the recruitment of IGF2BP1 promoted the transmission of hepatitis B/C and human papillomaviruses, which suggested that IGF2BP1 had various functions in different fields." (PMID 39342091, 2024).
Hyperglycemia (1 paper, 2023). An increased concentration of glucose in the blood. "IGF2BP1 and m6A-dependent modification may be one of the primary pathogenesis of vascular pathology and hyperglycemia." (PMID 37009154, 2023).
Hyperinsulinemia (1 paper, 2024). An increased concentration of insulin in the blood. "Since T1DM is different from the in obese and T2DM, especially considering the hyperinsulinemia, thus the antiatrophy ability of A. muciniphila may be dependent on the recovery of insulin signaling in muscle, evidenced by increased expression levels of Igf2r and Igf2bp1." (PMID 39429872, 2024).
insulinomas (1 paper, 2022). "To further investigate this hypothesis, we analyzed IGF2BP1 expression in insulinomas of 10–15 weeks old RIP1-Tag2 (RT) mice, a well-characterized pancreatic neuroendocrine tumor mouse model of ß-cell carcinogenesis." (PMID 35565249, 2022).
invasive breast carcinoma (1 paper, 2022). A carcinoma that infiltrates the breast parenchyma. "To clarify this area of focus, we analyzed the functional relationships between IGF2BP1 and clinical values in patients with invasive breast carcinoma (BRCA) via data mining of multiple databases and enrichment analysis." (PMID 36092925, 2022). "In the present study, we demonstrated genetic alterations (particularly amplification and overall upregulation) of IGF2BP1 in invasive breast cancer using large and publicly available datasets from METABRIC, TCGA, and GEO." (PMID 36092925, 2022). "We also herein confirmed IGF2BP1 to be a promising prognostic indicator in overall invasive breast cancer and in certain subgroups, including histologic types of IDC and postmenopausal subgroups and patients who did not undergo radiotherapy." (PMID 36092925, 2022).
leiomyoma (1 paper, 2022). A well-circumscribed benign smooth muscle neoplasm characterized by the presence of spindle cells with cigar-shaped nuclei, interlacing fascicles, and a whorled pattern. "The mean expression levels of miR-181a-5p, 127-3p, 28-3p, 30b-5p and let-7c-5p were higher in cases with TGFBR2 and IGF2BP1 positive leiomyoma." (PMID 35639702, 2022). "Particularly, the five miRs including miR-181a-5p, 127-3p, 28-3p, 30b-5p and let-7c-5p, and their target molecules including TGFBR2 and IGF2BP1, were up-regulated in leiomyoma tissues." (PMID 35639702, 2022). "IGF2BP1 was more frequently positive in patients with ≥ 6 cm leiomyoma, irregular menstruation and mass effect." (PMID 35639702, 2022). "Therefore, we strongly suspected that such changes in miR up-regulated TGFBR2 and IGF2BP1 in leiomyoma tissue and affected its growth." (PMID 35639702, 2022). "The mean expression levels of miR-181a-5p, 127-3p, 28-3p, 30b-5p and let-7c-5p were higher in patients with IGF2BP1 and TGFBR2-positive leiomyoma." (PMID 35639702, 2022). "We found that TGFBR2 and IGF2BP1 were positively stained in 13 (81%) and 10 (62.5%) leiomyoma tissues; however, neither of them was stained in the adjacent myometrium." (PMID 35639702, 2022). "TGFBR2 and IGF2BP1 were positively stained in 81% and 62.5% of leiomyoma tissues but not in adjacent myometrium." (PMID 35639702, 2022). "Leiomyoma tissues but not the adjacent myometrium stained positive for TGFBR2 and IGF2BP1." (PMID 35639702, 2022).
lentivirus infection (1 paper, 2023). Virus diseases caused by the Lentivirus genus. "Next, KYSE30 cells stably expressing shRNA of IGF2BP1 (shIGF2BP1) or nonsilencing shRNA (shNS) conducted by lentivirus infection were injected into nude mice via the tail vein." (PMID 37644505, 2023).
lymphoma (1 paper, 2017). A malignant (clonal) proliferation of B- lymphocytes or T- lymphocytes which involves the lymph nodes, bone marrow and/or extranodal sites. "IGF2BP1 and IGF2BP3 are re-expressed in several aggressive cancers in colorectal and lymphomas with a high incidence of more than 70%." (PMID 28693523, 2017).
male infertility (1 paper, 2025). The inability of the male to effect fertilization of an ovum after a specified period of unprotected intercourse. "Therefore, we hypothesize that IGF2BP1 plays an important role in controlling fate determinations of human SSCs and that its dysfunction may be associated with male infertility." (PMID 41280724, 2025).
meningioma (1 paper, 2018). A generally slow growing tumor attached to the dura mater. "IGF2BP1 increased the malignant potential of meningiomas, with significantly higher methylation levels in atypical (grade II/III) than benign (grade I), indicating its prognostic role." (PMID 29954406, 2018). "The significantly frequent promoter methylation of IGF2BP1 in recurrent meningioma cases was found." (PMID 29954406, 2018).
metabolic syndrome (1 paper, 2018). A cluster of metabolic risk factors for CARDIOVASCULAR DISEASES and TYPE 2 DIABETES MELLITUS. "Differences in mean DNA methylation (%) of (A) cg06500161 in ABCG1 and of (B) cg06638433 in IGF2BP1 gene by metabolic syndrome and components." (PMID 29643945, 2018).